NLRP3 (NLR family pyrin domain containing 3)
Diseases named in the same sentence as NLRP3 in open-access papers (continued):
Sharing a sentence is not in itself a finding about the gene and the disease.
kidney (continued). "Therefore, reducing the activation of the NLRP3 inflammasome is a reliable method to reverse the development of liver pyroptosis and fibrosis and effectively alleviates liver injury." (PMID 36900523, 2023). "Furthermore, depleted TLR9 levels restrained NF-κB viability and NLRP3 expression and reduced kidney inflammation, microalbuminuria discharge, blood sugar level, and glomerular damage in experimental mice (db/db) kidneys." (PMID 35120573, 2022). "In particular, we examined whether altered mitochondrial viability and dynamics induced by activation or suppression of PGC-1α can regulate the NLRP3 inflammasome pathway, and thus affect kidney injury." (PMID 35013155, 2022). "Moreover, DHB was also found to possess renoprotective effect, at least in part by inhibiting NLRP3 inflammasome activation to mitigate kidney inflammation and dysfunction." (PMID 33959014, 2021). "Collectively, these results suggested that ceftriaxone calcium crystals could induce acute kidney injury by NLRP3-mediated inflammation and oxidative stress injury." (PMID 32695257, 2020). "Critical roles for NLRP3 have been found in the regulation of liver IR injury." (PMID 32666684, 2020). "Furthermore, NLRP3 inhibition in the macrophages decreased neutrophil infiltration and promoted Tregs activation in the both young and aged mice post‐liver IR." (PMID 32666684, 2020). "Suppression of inflammasome activation by knocking out ASC prevented tubulointerstitial injury in the eNOS knockout mice, indicating that the eNOS–NO pathway is involved in the development of kidney dysfunction through acceleration of NLRP3 inflammasome in macrophages." (PMID 30281670, 2018). "Suppression of inflammasome activation by knocking out ASC prevented tubulointerstitial injury in eNOS KO mice, indicating that the eNOS–NO pathway is involved in the development of kidney dysfunction through acceleration of the NLRP3 inflammasome in macrophages." (PMID 30281670, 2018). "Our study indicates that lung IR inflammation is mediated by the NLRP3 inflammasome and IL-1β and may have beneficial effects to the host in the context of superimposed bacterial lung infection." (PMID 29163464, 2017). "In addition, a growing body of evidence suggested that dihydroberberine, the derivative of BBR, could inhibit NLRP3 inflammasome activation to mitigate kidney inflammation and dysfunction." (PMID 37193772, 2023). "Moreover, dietary supplementation with genistein has been shown to alleviate fatty liver conditions in hyperlipidemic laying hens through up-regulation of estrogen receptor alpha (ERα) expression while inhibiting the expression of the NLR family pyrin domain containing 3 (NLRP3) inflammasome." (PMID 38997768, 2024). "Suppresses NLRP3, caspase-1 and ASC expression and prevents acute kidney injury induced by lipopolysaccharide." (PMID 35566359, 2022). "Endogenous extracellular histones activated the NLRP3 inflammasome in macrophages through TLR9, which triggered sterile inflammation during liver IR injury." (PMID 32666684, 2020). "Despite the growing number of related studies, a comprehensive and systematic review summarizing the role of the NLRP3 inflammasome in urogenital cancers and its potential therapeutic strategies is still lacking." (PMID 40718836, 2025). "The present study showed that PGC-1α mitigated mitochondrial damage and oxidative stress levels, restored mitochondrial integrity and TNFAIP3, and attenuated the activation of the NLRP3 inflammasome pathway in the TGF-β-treated RTECs and animal models of kidney injury." (PMID 35013155, 2022). "The study aimed to explore whether the mechanism of rapamycin inhibits the activation of NLRP3 inflammatory bodies by regulating mTOR, to explore the therapy of OSA-induced kidney injury." (PMID 35184679, 2022).
kidney (continued). "To determine whether kidney dysfunction upregulates the NLRP3 inflammasome complex in atria, we adopted the previously established 2-stage subtotal nephrectomy protocol to create a CKD model in WT (WT-CKD) and Nlrp3-knockout CKD (Nlrp3–/–-CKD) mice." (PMID 37581942, 2023). "Although 66PR recovered kidney function failure induced by hemes through NLRP3 inhibition, we do not know whether the liver, lung, brain, and other organ function, as well as hematopoiesis, can be influenced or not." (PMID 33783986, 2021).
immune diseases (41 papers, 2018 to 2026). "Small-molecule inhibitors targeting the NLRP3 inflammasome promise a therapeutic benefit for a wide range of immune diseases including the CAPS mutant associated Muckle-Wells-Syndrome50." (PMID 36329210, 2022). "Recent studies have shown that the NLRP3 inflammasome is involved in a variety of adaptive immune diseases and that NLRP3 mutations could lead to chronic autoinflammatory syndrome." (PMID 37266449, 2023). "It is known that NLRP3 mutation confers susceptibility to immune disorders." (PMID 34956329, 2021). "Through its dual mechanisms of “direct NLRP3 inhibition” and “regulation of protein stability,” Tranilast provides multidimensional evidence supporting the repurposing of this drug for treating NLRP3-driven cardiovascular and immune disorders." (PMID 40520933, 2025). "Aging-related immune dysfunction often results in chronic activation of the NLRP3 inflammasome, contributing to lung inflammation, ARDS, and fibrosis." (PMID 40218944, 2025). "The NLRP3 inflammasome is closely related to RA, and its abnormal activation is important in guiding the inflammatory response and the development of immune diseases." (PMID 37954594, 2023). "MCC950 is a selective inhibitor of NLRP3 and has therapeutic effects on NLRP3-related inflammatory or immune diseases." (PMID 37360683, 2023). "Inflammasomes, in which NLRP3 inflammasome is the most studied signaling platform, have been widely reported in various inflammation and immune disorders." (PMID 36685554, 2022). "The activated NLRP3 inflammasome is one of the most important mediators of pyroptosis, which is involved in various inflammatory and immune diseases." (PMID 35496273, 2022). "Theory of neuroinflammation induced by activation of NLRP3 inflammasome suggests that congenital immune disorders and neuroinflammation play an important role in the pathogenesis of AD." (PMID 34381452, 2021). "Our results further suggest a possible therapeutic application of NLRP3 inflammasome inhibitors that would prevent the onset of NLRP3 inflammasome-mediated inflammatory and immune diseases." (PMID 31439870, 2019). "The NLRP3 inflammasome plays a key role in the inflammation process, and its aberrant activation leads to several inflammatory or immune diseases." (PMID 29558930, 2018). "NLRP3 (nucleotide-binding domain and leucine-rich repeat pyrin domain containing 3) inflammasome plays a key role in the inflammatory process, and its abnormal activation leads to a variety of inflammatory or immune diseases." (PMID 36713032, 2023). "Our findings suggest that strategies elevating MafB may be effective to treat immune disorders due to excessive activation of the NLRP3 inflammasome." (PMID 37845329, 2023). "This review outlines the role of the TLR/NLRP3/Cas-1 pathway in PD-related immune dysfunction, also focusing on specific therapeutic options that might be used since the early stages of the disease to counteract neuroinflammation and immune dysfunction." (PMID 36460875, 2023). "Decreased levels of IL-1β inhibit msu-induced activation of NLRP3 inflammatory vesicles, impede maturation and secretion of inflammatory cytokines, thereby reducing the recruitment of neutrophils and other cells and regulating immune disorders." (PMID 36313318, 2022). "Nevertheless, further preclinical trials are necessary to ascertain whether fisetin can downregulate NLRP3 inflammasome-induced immune disorders in humans." (PMID 34439462, 2021). "Further studies have shown that MCC950 can effectively inhibit NLRP3-related immune diseases." (PMID 29929501, 2018). "While the immune mechanism(s) of PAE-induced immune dysfunction are poorly understood, prior studies implicated the involvement of Toll-like receptor 4 (TLR4) and the nucleotide-binding domain, leucine-rich repeat-containing family, pyrin domain-containing 3 (NLRP3) inflammasomes." (PMID 40628342, 2025).
immune diseases (continued). "The NLRP3 inflammasome includes three protein subunits, the adaptor protein, apoptosis-associated speck-like protein containing a CARD (ASC), the receptor NLRP3, and the effector pro-caspase-1, and participates in various infectious, inflammatory, and immune diseases." (PMID 34059091, 2021). "Finally, as part of the NLRP3 activation in SARS-CoV-2 patients, recent studies support the hypothesis that the P2X7R/NLRP3 component may be involved in immune dysfunction caused by COVID-19 infection." (PMID 34681901, 2021). "The upregulation of NEAT1 has been shown to promote the release of several inflammasomes (NLRP3, NLRC4, and AIM2) and pro-inflammatory cytokines (CXCL10, IL-6, and IL-1β), resulting in an immune response in inflammatory and immune diseases." (PMID 35127819, 2021). "Accumulating data suggest that inflammasomes, mainly NLRP3, NLRP1, and AIM2, are involved in the generation of tissue damage and immune dysfunction after trauma." (PMID 30166988, 2018). "These mice and human studies support a relationship between the activation of NLRP3 inflammasomes and immune dysfunction in KD, but they do not clearly define what triggers the activation of NLRP3 in these models." (PMID 36300112, 2022).
respiratory diseases (26 papers, 2016 to 2026). "NLRP3-induced inflammation and the release of IL-1β and IL-18 are linked to various respiratory diseases." (PMID 40218944, 2025). "The NLRP3 inflammasome pathway has been implicated in various respiratory diseases." (PMID 40218944, 2025). "In summary, targeting the NLRP3 inflammasome is a viable strategy for inhibiting pyroptosis and treating respiratory diseases, whereas other targets, such as caspase-1, also exhibit therapeutic potential." (PMID 39300122, 2024). "Excessive inflammasome activation and pro-inflammatory cytokine production are involved in the pathogenesis of respiratory diseases, and NLRP3 inflammasomes have been suggested as potential targets for such diseases." (PMID 35418866, 2022). "Among the traditional signaling pathways, NLRP3 and caspase-1 play the most extensive role in respiratory diseases." (PMID 36248872, 2022). "A new understanding of the critical role of NLRP3 and NF-κB in triggering the antiviral innate immune response and aggravating the severity of the respiratory diseases during RSV infection is challenged." (PMID 35308390, 2022). "IL-1β is a pro-inflammatory cytokine involved as an effector of the NLRP3 inflammasome and is known to increase the incidence of respiratory diseases induced by PM2.5." (PMID 34684415, 2021). "Melatonin also has the ability to prevent the activation of NLRP3 inflammasome in respiratory disease and other disturbances." (PMID 34356384, 2021). "The NLRP3 inflammasome represents a key focus in respiratory disease research." (PMID 40832584, 2025). "Understanding the role of NLRP3 inflammasomes in these diseases could pave the way for targeted therapies and improved management of respiratory system disorders." (PMID 37686825, 2023). "Therefore, future study targeting the gut microbiota may offer a potential strategy for managing NLRP3 inflammation-related respiratory diseases." (PMID 40218944, 2025). "However, it should be noted that previous studies have also suggested neutrophils-mediated inflammatory responses play an important role in the pathogenesis of several respiratory diseases, among which S1P signaling and NLRP3 inflammasome might be vital ones." (PMID 36653338, 2023). "Recently, it has been shown that erythropoietin (EPO), employed for the treatment of anemia, also demonstrates therapeutic effects in respiratory disorders such as ALI, as it suppresses the NLRP3 inflammasome." (PMID 38068879, 2023). "Even though the mechanism of activation and action of the NLRP3 inflammasome is well understood, its influence on the development of respiratory diseases is not fully investigated." (PMID 36203607, 2022). "Of the respiratory diseases discussed here, we highlight the host initiation of pyroptosis through the non-canonical inflammasome, as well as the AIM2 and NLRP3 inflammasomes." (PMID 35626718, 2022).
psychiatric disorder (24 papers, 2019 to 2025). A disorder characterized by behavioral and/or psychological abnormalities, often accompanied by physical symptoms. "The molecular structure of NLRP3 and its role in the neuroinflammatory cascade are presented, along with potential pharmacological strategies for modulating the activity of this complex in the context of treating mental disorders associated with chronic stress." (PMID 41008651, 2025). "Clinically, persistent HPA axis hyperactivation and NLRP3 inflammasome signaling contribute to neuroinflammatory pathology across multiple psychiatric disorders." (PMID 41008651, 2025). "Patients with psychiatric disorders exhibit increased levels of these receptors, such as TLRs in monocytes and peripheral lymphocytes, and NLRP3 in blood cells and the frontal cortex." (PMID 39452916, 2024). "In this study, immunometabolites with known regulatory effects on the NLRP3 inflammasome and the production of IL-1 family cytokines were investigated in markedly ill individuals with severe psychiatric disorders and in age and sex-matched healthy controls." (PMID 37076825, 2023). "In numerous psychiatric disorders, elevated levels of IL-1 and IL-18 serve as indicators for the activation of the NLRP3 inflammasome." (PMID 38026692, 2023). "Glymphatic impairment can lead to ROS accumulation in the microenvironment, inducing cellular injury signaling and activating NLRP3 in microglia to induce inflammation and, thus, many brain diseases, including psychiatric disorders." (PMID 36421482, 2022). "The contribution of NLRP3 activation towards pathophysiology and behavioral deficits in neurocognitive disorders and psychiatric disorder has emerged as an active area of investigation." (PMID 34895246, 2021). "The NLRP3 inflammasome has also received attention in the literature pertaining to psychiatric disorders." (PMID 34895246, 2021). "In psychiatric disorders, postmortem brain samples from bipolar patients demonstrated the activation of NLRP3 as compared to controls." (PMID 32121312, 2020). "The activation of nod-like receptor family pyrin domain containing 3 (NLRP3) is closely related to mental illness." (PMID 32166013, 2020). "In support of this view, several studies in animal models of accelerated senescence, AD, PD, MS, ALS, and psychiatric disorders have shown a pivotal role of NLRP3 inflammasome in the onset and progression of central neuroinflammation and neurodegeneration." (PMID 31200447, 2019). "Moreover, inflammation, including NLRP3 activation, has been suggested to be important in both psychiatric disorders and VTE." (PMID 40093964, 2025). "Therefore, the NLRP3 inflammasome can be a potential target to treat aggressive behavior-related mental illnesses." (PMID 36778007, 2023). "NLRP3 activation appears to bridge the gap between immune activation and metabolic danger signals or stress exposure, which are important factors in the pathogenesis of psychiatric disorders." (PMID 35295780, 2022). "Of interest, various phytochemicals have been found to inhibit NLRP3 activation acting on different steps of the inflammasome cascade and to exert beneficial effects in experimental models of CNS diseases, including PD, AD, MS, and psychiatric disorders." (PMID 31200447, 2019). "Together, our study findings indicate that the gut microbiota contributes to both hippocampal NLRP3-mediated neuroinflammation and depressive-like behavior induced by CEE, which may open avenues for potential interventions against CEE-associated psychiatric disorders." (PMID 36280756, 2023). "Taken together, the study reveals that among immunometabolites with known effect on inflammation and in particular the NLRP3 inflammasome and the IL-1 family cytokines, lactic acid, serine, and glutamine are increased in individuals with psychiatric disorders irrespective of primary diagnosis." (PMID 37076825, 2023).
psychiatric disorder (continued). "It is safe to conclude that central inflammasome activation, mainly concerning microglial NLRP3, is a decisive and course-setting event in the development and perpetuation of neurological and psychiatric disorders, regardless of whether they are acute or chronic." (PMID 32466593, 2020).